APOA5 (apolipoprotein A5)
Diseases named in the same sentence as APOA5 in open-access papers (continued):
Sharing a sentence is not in itself a finding about the gene and the disease.
hypertriglyceridemia (continued). "Collectively, although the genetic variants of CETP might affect the efficacy of statins to reduce cardiovascular risk, and the variants of APOA5 may be associated with hypertriglyceridemia, further studies are needed to elucidate the exact meaning of the findings in this study." (PMID 35664336, 2022). "In IFG or diabetic individuals found to carry the APOA5 -1131C variant, therefore, the replacement of refined rice with whole grains and legumes in a high carbohydrate diet may need to be considered to prevent diabetic hypertriglyceridemia." (PMID 24690159, 2014). "Similarly, inherited apoA5 gene deficiency is associated with severe hypertriglyceridemia in human." (PMID 24016248, 2013). "Furthermore, apoA5 gene is regulated by proinflammatory cytokines and apoA5 may be involved in inflammation-associated hypertriglyceridemia." (PMID 24016248, 2013). "APOA5 and LPL LOF variants are associated with hypertriglyceridemia yet few missense variants are associated with these clinical phenotypes." (PMID 40473624, 2025). "Our findings confirm that polymorphisms at the APOA5 rs2075291 and CIDEB rs2144492 loci are associated with hypertriglyceridemia." (PMID 41179497, 2025). "Similar to APOA5, ZPR1 regulates TC, HDL and TG levels and has been associated with hypertriglyceridemia, metabolic syndrome and type 2 diabetes mellitus." (PMID 40830362, 2025). "This study confirms that APOA5 rs2075291 and CIDEB rs2144492 polymorphisms are associated with hypertriglyceridemia." (PMID 41179497, 2025). "Later in vivo studies demonstrated that the hypertriglyceridemia in APOA5 KO mice results from decreased intracapillary LPL amounts in oxidative tissues and that an anti-A3/8 antibody normalizes circulating TG concentrations in these mice." (PMID 38521668, 2024). "Now, two decades after the discovery of APOA5 and the discovery of severe hypertriglyceridemia in Apoa5−/− mice, the molecular physiology of APOA5 has come into focus." (PMID 38880127, 2024). "Our studies revealed that the severe hypertriglyceridemia in Apoa5–/– mice was accompanied by substantial reductions in LPL mass and activity in the postheparin plasma." (PMID 37824203, 2023). "Our studies explain the hypertriglyceridemia in Apoa5–/– mice and further illuminate the molecular mechanisms that regulate plasma TG metabolism." (PMID 37824203, 2023). "Our studies explained the hypertriglyceridemia in Apoa5–/– mice and increased our understanding of the mechanisms that regulate plasma TG metabolism." (PMID 37824203, 2023). "The most severe type of HTG is primary (or hereditary) hypertriglyceridemia, linked to pathogenic genetic variants in LPL, APOC2, LMF1, and APOA5 genes." (PMID 35741823, 2022). "Indeed, apoA5 has been documented as a target of several triglyceride-lowering drugs, and we previously demonstrated that apoA5 is implicated in the amelioration of hypertriglyceridemia in mice by metformin, a drug for olanzapine-induced glucose and lipid disorder." (PMID 36034782, 2022). "Most variants interfering with triglyceride metabolism and causing hypertriglyceridemia are loss of function variants (LOF), and mainly found in the LPL, APOC2, APOA5, LMF1 and GPIHBP1 genes." (PMID 35237305, 2022). "Here, the role of apolipoprotein A5 (apoA5), a regulator of triglyceride metabolism, was investigated in olanzapine-induced hypertriglyceridemia." (PMID 36034782, 2022). "A GWA study of individuals with hypertriglyceridemia has shown that common variants in 4 genetic loci (APOB, LPL, GCKR, and APOA5) are significantly related to increased TG levels." (PMID 35999587, 2022). "Together, these data suggested the implication of apoA5 in olanzapine-induced hypertriglyceridemia, which was to be determined in this study." (PMID 36034782, 2022). "In this study, the role of apolipoprotein A5 (apoA5) in the development of olanzapine-induced hypertriglyceridemia was investigated." (PMID 36034782, 2022).
hypertriglyceridemia (continued). "Meanwhile, reduced apoA5 secretion resulted in decreased plasma apoA5 levels and suppression of hydrolysis for plasma triglyceride, ultimately leading to hypertriglyceridemia." (PMID 36034782, 2022). "For severe hypertriglyceridemia, pathogenic variants in genes LPL, APOA5, APOC2, GPIHBP1, and LMF1, associated with hyperlipidemia should be considered." (PMID 36051701, 2022). "Together, these data suggested that apoA5 plays an important role in olanzapine-induced hypertriglyceridemia." (PMID 36034782, 2022). "To investigate the role of apoA5 in olanzapine-induced hypertriglyceridemia, we measured apoA5 expression at both the protein and the mRNA levels in mouse livers." (PMID 36034782, 2022). "A set of 53 single nucleotide polymorphisms (SNPs) previously associated with triglycerides levels, as well as 37 rare variants within the five main genes associated with hypertriglyceridemia (i.e. LPL, APOC2, APOA5, LMF1 and GPIHBP1) were analyzed." (PMID 33588820, 2021). "Variants on genes known to cause severe hypertriglyceridemia such as LPL, APOC2, GPIHBP1, APOA5, and LMF1 were first selected and interpreted." (PMID 32765589, 2020). "This is different from that of APOA5 c.553G>T heterozygous mice which synthesized half of functional APOA5 protein and capably hydrolyzed postprandial hypertriglyceridemia." (PMID 29425239, 2018). "Similar phenomena were observed in other hypertriglyceridemia-related diseases, including type 2 diabetes, severe hypertriglyceridemia, and acute coronary syndrome, where plasma apoA5 levels were elevated and positively correlated with TG." (PMID 29312569, 2017). "Consistent with this notion, the 1131T>C single nucleotide polymorphism (SNP) in the apolipoprotein A5 gene (APOA5) is associated with an increased risk of CAD in several ethnic populations, probably due to its association with hypertriglyceridemia." (PMID 29211729, 2017). "It was consistent with our previous findings that revealed that high-fructose diet can induce hypertriglyceridemia in rats by inhibiting hepatic apoA5 expressions." (PMID 28934253, 2017). "Transgenic mice overexpressing ApoA5 displayed lower levels of plasma TGs compared with WT mice, whereas ApoA5 knockout mice developed hypertriglyceridemia." (PMID 25548259, 2015). "In summary, the present study demonstrates that reducing hepatic ApoA5 expression in mice by ASO treatment reduces LPL activity leading to hypertriglyceridemia and decreased lipid uptake by liver, muscle, and WAT." (PMID 25548259, 2015). "In a dietary trial in Korean patients with hypertriglyceridemia, APOA5 T-1131T homozygotes showed larger decrease in plasma TG after combined dietary and exercise intervention." (PMID 24462044, 2014). "Severe hypertriglyceridemia (HTG) has been linked to defects in LPL, APOC2, APOA5, LMF1 and GBIHBP1 genes." (PMID 23151256, 2012). "APOA5 knockout mice develop hypertriglyceridemia, whereas transgenic mice overexpressing APOA5 have low TG levels." (PMID 20696075, 2010). "Study has shown that APOA5 knockout mice develop hypertriglyceridemia, whereas transgenic mice overexpressing APOA5 have low triglyceride levels." (PMID 20696075, 2010). "This study reports for the first time the association between APOA5 rs2075291 and CIDEB rs2144492 polymorphisms and hypertriglyceridemia in a dampness syndrome population, offering critical insights for investigating triglyceride metabolism in TCM dampness syndrome cohorts." (PMID 41179497, 2025). "APOA5 rs2075291 and CIDEB rs2144492 polymorphisms are associated with hypertriglyceridemia." (PMID 41179497, 2025). "Notably, rs2266788 in APOA5 modifies atorvastatin response in stroke patients and exacerbates antipsychotic-induced hypertriglyceridemia in schizophrenia (SCZ), underscoring its relevance in neuropsychiatric disorders." (PMID 40869228, 2025).
hypertriglyceridemia (continued). "•APOA5’s ability to bind and suppress ANGPTL3/8 is utterly dependent on the last ∼40 amino acids of APOA5, explaining why APOA5 truncation mutations in humans cause severe hypertriglyceridemia." (PMID 38880127, 2024). "rs2072560 is located in the intron of APOA5, whereas rs2266788 is located in the 3’-untranslated region(UTR) of APOA5; rs2266788 has been reported in ClinVar as a potential risk variant for familial hypertriglyceridemia (ClinVar Accession number SCV000148905)." (PMID 39198834, 2024). "Familial hypertriglyceridemia is the result of a single gene mutation, usually in the lipoprotein lipase (LPL) or ApoC2 or ApoA5 genes involved in TG metabolism, and manifests as severe hypertriglyceridemia (TG > 10 mmol/L) with an incidence of about 1 in 1 million." (PMID 37711173, 2023). "Meanwhile, the proband and his children carried an APOA5 gene mutation, which is considered a suspected pathogenic variant resulting in hypertriglyceridemia or hyperlipoproteinemia independent of the SCN5A mutation." (PMID 37288251, 2023). "APOA5 plays an important role in the pathophysiology of insulin resistance-related hypertriglyceridemia; obese human participants had lower plasma APOA5 levels, which were inversely correlated with TGs, body mass index and homeostasis model assessment of insulin resistance (HOMA-IR)." (PMID 35628864, 2022). "However, the prevalence rate of hypertriglyceridemia (triglyceride ≥ 1.7 mmol/L) showed a significant inverted “U”-shaped trend in individuals with the serum ApoA5 level of quartile one to quartile four after adjusting the confounding factors." (PMID 35854768, 2022). "Severe hypertriglyceridemia, in the form of Familial Chylomicronaemia Syndrome (FCS), is a rare autosomal recessive disease caused by pathogenic variants especially in the LPL gene but also in APOC2, APOA5, LMF1 and GPIHBP1." (PMID 35237305, 2022). "The mutated apoA5 was intracellularly missorted to lipid droplets and not secreted, leading to undetectable apoA5 plasma levels, and consequently severe hypertriglyceridemia." (PMID 36034782, 2022). "However, olanzapine treatment led to defective hepatic apoA5 sorting and secretion, thereby reducing plasma apoA5 levels and resulting in hypertriglyceridemia." (PMID 36034782, 2022). "Therefore, our study indicated that short-term use of olanzapine induced hypertriglyceridemia due to defects of sorting and secretion of hepatic apoA5." (PMID 36034782, 2022). "Here, we proposed a hypothesis for the role of apoA5 in hypertriglyceridemia induced by short-term use of olanzapine." (PMID 36034782, 2022). "Given that apoA5 is a liver-specific protein, we initially speculated that olanzapine-induced reduction of plasma apoA5 levels could be a consequence of decreased hepatic apoA5 production, leading to hypertriglyceridemia." (PMID 36034782, 2022). "In Mexico, hypertriglyceridemia constitutes a health problem in which the genetic bases have been scarcely explored; therefore, our objective was to describe biochemical–clinical characteristics and variants in the APOA5, GPIHBP1, LMF1, and LPL genes in patients with primary hypertriglyceridemia." (PMID 36613909, 2022). "Variants in the lipoprotein lipase (LPL), apolipoprotein C-II (APOC2), apolipoprotein A-V (APOA5), GPIHBP1 and LMF1 genes may cause severe hypertriglyceridemia (HTG), which is now the second-leading aetiology of acute pancreatitis in China." (PMID 29921298, 2018). "Interestingly, accumulated data implicate the potential role of apolipoprotein A5 (apoA5) in the crosstalk between hypertriglyceridemia and NAFLD." (PMID 29312569, 2017). "ApoA5 plays a role in elevating HDL levels and is closely associated with hypertriglyceridemia." (PMID 27724895, 2016). "The hypertriglyceridemia observed after ApoA5 knockdown might lead one to hypothesize that ApoA5 knockdown would diminish tissue insulin sensitivity." (PMID 25548259, 2015).
hypertriglyceridemia (continued). "In this study we found a gene-diet interaction for the 668 A/G polymorphism in the LEPR gene and 56 C/G in the APOA5 gene with a high intake of saturated fatty acids (SFA) and total fat was associated with obesity, hypercholesterolemia and hypertriglyceridemia." (PMID 26365669, 2015). "Recent findings indicate that ApoA5 could also influence cholesterol homeostasis and probably could play a role in hypertriglyceridemia." (PMID 25515090, 2014). "Serum apoA5 elevation after statin and fibrate combination treatment could be due to the synergistic effect of both drugs on hypertriglyceridemia control." (PMID 24016248, 2013). "One primary objective of this study is to assess the association between the haplotypes in apolipoprotein A5 gene (APOA5) and hypertriglyceridemia in humans, adjusting for the environmental covariates Age, Sex, and BMI, and to explore the potential haplotype-environment interactions." (PMID 16907993, 2006). "The differences in the prevalence of decreasing serum HDL-C and elevating serum TG levels according to SCG together with APOA5 −1131T>C polymorphism suggest that SCG may act as a significant risk factor of hypo-HDL-C-emia and hypertriglyceridemia susceptibility." (PMID 21860654, 2012). "Taken together, our results shed light on a novel intersection of ApoA5 and the ANGPTL3/4/8 family of proteins in the regulation of TG metabolism and also provide a possible explanation for LXR agonist–induced hypertriglyceridemia." (PMID 33762177, 2021). "Together, these results reveal a novel intersection of ApoA5 and ANGPTL3/8 in the regulation of TG metabolism and provide a possible explanation for LXR agonist-induced hypertriglyceridemia." (PMID 33762177, 2021). "This study expands the functional scope of APOA5 in TG metabolism and underscores its role in VLDL remodeling and remnant clearance, offering new insights with implications for understanding hypertriglyceridemia and its roles in inflammation and immune response." (PMID 41043689, 2025). "Besides LPL, there are other genes involved in primary hypertriglyceridemia phenotypes (most notably, APOC2, APOA5, LMF1, and GPIHBP1)." (PMID 36051701, 2022). "Therefore, our findings indicated that olanzapine-induced reduction of plasma apoA5 levels could result from the retardation of hepatic apoA5 secretion (rather than hepatic apoA5 production/synthesis), which consequently led to hypertriglyceridemia." (PMID 36034782, 2022). "In 2012, we found an excessive prevalence of rare variants in LPL, APOC2, GPIHBP1, APOA5, and LMF1 in patients with severe hypertriglyceridemia, again indicating that heterozygosity was a predisposing factor for, although not an absolute cause of severe hypertriglyceridemia or MCM." (PMID 32793115, 2020).
dyslipidemia (79 papers, 2008 to 2025). "There have been few studies in adult populations demonstrating that the presence of the C allele of the rs 662799 polymorphism in the APOA5 gene is associated with dyslipidemia." (PMID 40428368, 2025). "A Chinese community-based cohort including 4329 adults showed that BMI significantly modulated the APOA5 rs662799 genetic effects on dyslipidemia risk, in line with the BMI–APOA5 rs662799 interaction on TG." (PMID 38917408, 2024). "APOA5 deficiency can exert some influences on obesity, as an additional element of metabolic syndrome." (PMID 38867151, 2024). "For example, the APOA5 gene was found associated with familial combined hyperlipidemia and dyslipidemia in large dutch families, and in an italian population." (PMID 36782330, 2023). "Some studies have reported that the APOA5 gene is clearly associated with the establishment of cardiovascular events and metabolic syndrome." (PMID 35745158, 2022). "Hypermethylation in exon 3 of the APOA5 gene had a positive correlation with the lipoprotein profile and TG concentration linked to atherogenic dyslipidemia." (PMID 35928108, 2022). "The APOA5 gene rs662799 was most associated with dyslipidemia (P = 1.40 × 10− 67); this association was maintained during the replication stage (CAVAS P = 3.69 × 10− 8, KARE P = 1.47 × 10− 11)." (PMID 36419087, 2022). "The APOA5 gene rs9804646 was most associated with dyslipidemia (P = 1.25 × 10− 32); this association was maintained during the replication stage (CAVAS P = 1.02 × 10− 6, KARE P = 2.52 × 10− 6)." (PMID 36419087, 2022). "It is well known that APOA5 SNP rs662799 is strongly associated with metabolic syndromes and elevated plasma TG." (PMID 35886029, 2022). "A previous genetical study confirmed an association of dyslipidemia with apolipoprotein A5 gene-1131T/C polymorphism as a powerful promotor of CHD." (PMID 36429701, 2022). "The APOA5 gene rs9804646 was the most associated with dyslipidemia (P = 7.31 × 10− 87); this association was maintained during the replication stage (CAVAS p = 8.64 × 10− 4, KARE P = 4.29 × 10− 4)." (PMID 36419087, 2022). "Additional APOA5 SNPs are associated with lipid levels, metabolic syndrome and statin treatment efficacy." (PMID 35327951, 2022). "The APOA5 rs662799 SNP showed a significant association with the risk for metabolic syndrome in various ethnic groups including Korean, Chinese, and Hungarian." (PMID 35174233, 2022). "While the association of the serum ApoA5 level, metabolic syndrome, and NAFLD in the general population of China is still unclear." (PMID 35854768, 2022). "In another twin study, a SNP (rs651821) in the apolipoprotein A5 (APOA5) gene was associated with the abundance of Bifidobacterium in patients with metabolic syndrome." (PMID 34159422, 2021). "This current study showed that carriers of the minor allelic variant of the APOA5 (rs662799) A>G SNP gene, were 2 times more likely to developed dyslipidemia." (PMID 31929604, 2020). "In this study, we constructed GRSs composed 7 genetic variants (ANGPTL3 rs10889353, APOB rs7557067, GCKR rs780092, C2orf16 rs1919127, TRIB1 rs2954029, FADS1-FADS2-FADS3 rs174547, and APOA5 rs2266788) associated with dyslipidemia using GWAS studies." (PMID 33339179, 2020). "Numerous evidence has demonstrated for an association between apoA5 and the increased risk of obesity and metabolic syndrome, but the mechanism remains to be fully elucidated." (PMID 30053818, 2018). "More recently, Ajjemami investigated the relative contribution of commons APOA5 SNPs and haplotypes to the risk of metabolic syndrome in Moroccan patients." (PMID 30053818, 2018). "Niculescu and colleagues used a case-control design to determine the association of two APOA5 gene SNPs in a group of urban Romanian subjects with metabolic syndrome." (PMID 30053818, 2018).